GPX4 (glutathione peroxidase 4)
Diseases named in the same sentence as GPX4 in open-access papers (continued):
Sharing a sentence is not in itself a finding about the gene and the disease.
osteosarcoma (continued). "Some tumor cell lines (possibly containing drug-resistant osteosarcomas) are also found to be resistant to ferroptosis burst when GPX4 is inhibited along with the acyl-CoA synthetase long-chain family member 4 (ACSL4) expression." (PMID 35402247, 2022). "MicroRNA-1287-5p promotes ferroptosis in osteosarcoma cells by inhibiting GPX4, but its expression is downregulated in human osteosarcoma relative to controls." (PMID 35837104, 2022). "Previous studies on the role of ferroptosis in osteosarcoma mainly targeted GPX4 and reported encouraging results." (PMID 35402247, 2022). "For illustration, it was found that inhibition of STAT3/Nrf2/GPX4 signaling induced ferroptosis sensitization, thereby enhancing the sensitivity of osteosarcoma cells to cisplatin." (PMID 35837104, 2022). "Recent studies have shown that the inducing ferroptosis by blocking STAT3/Nrf2/GPx4 signaling makes osteosarcoma cells more sensitive to cisplatin." (PMID 35774794, 2022). "In another study, miR-1287-5p expression was down-regulated in human osteosarcoma and promoted ferroptosis in osteosarcoma cells by inhibiting GPX4." (PMID 36135094, 2022). "Reduced GPX4 protein levels in osteosarcoma result in iron death and enhanced cisplatin sensitivity." (PMID 36157228, 2022). "Moreover, the upregulation of lncRNA PVT1 has been shown to facilitate the development of osteosarcoma by activating the STAT3/GPX4 axis, thereby reducing ferroptosis and modulating GSH and ROS levels." (PMID 40403492, 2025). "The signaling pathway involving STAT3/Nrf2/GPX4 is integral to the resistance observed in osteosarcoma cells and may serve as a promising therapeutic target to improve the effectiveness of cisplatin against bone tumors." (PMID 40740786, 2025). "This demonstrates that the GPX4 protein can be utilized as a target for osteosarcoma medicines." (PMID 40969276, 2025). "In addition, EF24, as a synthetic analogue of CUR, significantly induced cell death, elevatedHMOX1 expression, inhibited GPX4 expression, and promoted ferroptosis in osteosarcoma cell lines by elevating intracellular MDA, ROS and ferric ion levels." (PMID 40552277, 2025). "ROS, lipid peroxides and MDA levels were lower in cisplatin resistant osteosarcoma cells, which may be related to the increase of antioxidant enzymes such as GPX4." (PMID 38469234, 2024). "Moreover, we used RSL3, a known inducer of ferroptosis, to promote GPX4 degradation and found that the reduction in GPX4 levels in OTULIN-knockdown osteosarcoma cells was further accelerated by treatment with RSL3 together with CHX." (PMID 39721999, 2024). "However, we provide novel evidence that OTULIN deficiency promotes the ubiquitination of GPX4, including linear ubiquitin and K48, in osteosarcoma cells, which promotes the proteasomal degradation of GPX4." (PMID 39721999, 2024). "Moreover, HMOX1 overexpression induces ferroptosis by suppressing GPX4 expression in osteosarcoma cells." (PMID 39857625, 2024). "Collectively, these findings indicate that GPX4 could be a downstream target of OTULIN that confers resistance to cisplatin in osteosarcoma by blocking the mitochondrial apoptotic pathway." (PMID 39721999, 2024). "Sulfasalazine and miR-1287-5p mimics could inhibit GPX4 to promote ferroptosis in osteosarcoma cells." (PMID 39712490, 2024). "Meanwhile, the reduction of STAT3 and GPX4 leads to increased ferroptosis in osteosarcoma cells." (PMID 36814203, 2023). "Furthermore, synergistic growth inhibition in hypoxic osteosarcoma has been achieved by the induction of ferroptosis and substantial GPX4 downregulation using ultrasound-activated doxorubicin (DOX)-Fe(VI)@HMS-HE-PEG (DFHHP) nanoparticles." (PMID 37576601, 2023). "In addition, under hypoxia conditions, the prodrug tirapazamine was reported to decrease proliferation and induce ferroptosis in osteosarcoma 143B and U2OS cells; the biological functions were linked to the inhibition of SLC7A11 and GPX4." (PMID 36819098, 2023).
osteosarcoma (continued). "The study identified that ferroptosis sensitization could be induced by dampening STAT3/Nrf2/GPx4 signaling to enhance the sensitivity of osteosarcoma cells to cisplatin." (PMID 35402247, 2022). "Similarly, DHODH inhibitors are suggested to trigger ferroptosis through mitochondrial lipid peroxidation on those osteosarcoma cells with low GPX4 expression levels." (PMID 35402247, 2022). "The vital gatekeeper of ferroptosis, GPX4, was first reported to be involved in osteosarcoma." (PMID 35402247, 2022). "However, when BP-1-102, a STAT3 inhibitor, was used, the expression levels of NRF2 and GPX4 were strikingly decreased, which reactivated ferroptosis and enhanced the sensitivity of osteosarcoma cells to cisplatin." (PMID 36557902, 2022). "More trials are needed to determine whether GPX4 inhibitors can benefit osteosarcoma patients." (PMID 40969276, 2025). "Therefore, induction of ferroptosis by blocking the FSP1/CoQ10 axis with concomitant GPX4 blockade may have positive effects on osteosarcoma treatment." (PMID 35402247, 2022). "In osteosarcoma cells, the derivative EF24 activates heme oxygenase 1 (HMOX1) in a dose-dependent manner while suppressing GPX4 expression, resulting in increased intracellular levels of MDA, ROS, and Fe2+." (PMID 41515171, 2025). "Our data suggest that ferroptosis induction in undifferentiated hBMSCs is primarily regulated by GPX4, whereas glutathione S-Transferase P1 (GSTP1) plays a key role in controlling ferroptosis in osteosarcoma cells." (PMID 40002376, 2025). "Downregulation of miR-1231 and miR-188–3p increased GPX4 expression and intracellular GSH levels, thereby suppressing ferroptosis and promoting progression in papillary thyroid cancer and osteosarcoma, respectively." (PMID 40403492, 2025). "However, there have been few research on GPX4 protein inhibitors and osteosarcoma, therefore it can only be postulated that GPX4 may be involved in the prevention of osteosarcoma cell proliferation, migration, and invasion by acting as the key node for triggering ferroptosis." (PMID 40969276, 2025). "In osteosarcoma MNNG/HOS/MG-63 cells and corresponding animal models, curcumin cooperatively regulates the Nrf2, SLC7A11, HO-1, and GPX4 signaling axis, resulting in abnormal accumulation of ROS and MDA, and the collapse of the GSH antioxidant system." (PMID 41515171, 2025). "What's more, the tirapazamine (TPZ) can also downregulate the expression level of SLC7A11 and GPX4 and increase the level of MDA and Fe2+ which can lead to osteosarcoma cell produce more ROS inducing ferroptosis." (PMID 38800967, 2024). "In this research, we detected the role of FANCD2 on ferroptosis of osteosarcoma cells, FANCD2 knockdown reduced the levels of FTH1 and GPX4, and elevated COX2, increased the levels of iron, LIP, Fe2+, and promoted lipid peroxidation." (PMID 36814203, 2023). "In conclusion, targeting GPX4, FSP1, GCH1, and DHODH has a great potential for combating osteosarcoma." (PMID 35402247, 2022). "Additionally, TW80-SeNPs were gradually metabolized into selenoproteins (Gpx4 and TR1) into human osteosarcoma MG63 cells to reinforce the anticancer effect of NK92 cells by regulating the redox balance in the tumor microenvironment." (PMID 39634308, 2022). "Moreover, in osteosarcoma cells, overactivation of STAT3/NRF2 signaling can lead to cisplatin resistance by increasing glutathione peroxidase 4 (GPX4) activity, thereby suppressing ferroptosis." (PMID 36557902, 2022).
osteosarcoma (continued). "Since our study reveals that zoledronic acid promotes ferroptosis through decreasing cellular CoQ10 level, which is independent from the inhibition of GPX4 by RSL3, this explains the additive inhibitory effects of combining these two drugs on the growth of osteosarcoma cells." (PMID 36686696, 2022). "Furthermore, suppression of GPX4 and SOD2 reversed resistance to EGFR-TKIs in NSCLC and the induction of ferroptosis by impairing STAT3/Nrf2/GPx4 signaling enhances the sensitivity of osteosarcoma cells to cisplatin." (PMID 39681067, 2024).
colitis (44 papers, 2020 to 2026). Inflammation of the colon. "Taken together, this study evaluates that XYP alleviates DSS-induced colitis mice by inhibiting ferroptosis of enterocytes and its protective effects are associated with activating the Nrf2/Gpx4 signaling pathway." (PMID 41424783, 2025). "IBD patients’ epithelium exhibit significant reduced GPX4 activity and features of lipid peroxidation, and genetic loss of GPX4 aggravated the clinical outcome of chemically induced colitis." (PMID 35974396, 2022). "These suggested that SYD inhibited ferroptosis in epithelial cells and restored epithelial barrier loss in colitis in GPX4-dependent manner." (PMID 35974396, 2022). "Additionally, a high manganese diet heightened susceptibility, while a low manganese diet reduced DSS-induced colitis in colon epithelial-specific GPX4-deficient mice." (PMID 38260380, 2024). "Furthermore, PRDX1 deficiency suppressed azoxymethane (AOM)/dextran sodium sulfate (DSS)-induced colitis-associated CRC in mice possibly by inducing ferroptosis through the NRF2/GPX4 pathway." (PMID 39430237, 2024). "Study has shown that inhibition of ferroptosis through regulating iron load and GPX4 expression significantly alleviates epithelial cell death and promotes recovery in colitis models." (PMID 41573719, 2025). "Consistent with enhanced ferroptosis in colitis, GPX4 expression was significantly decreased in DSS-treated mice compared with controls, supporting the activation of ferroptosis in this model." (PMID 41515900, 2025). "The results suggested that the alleviating effects of GSH-Se on mouse colitis was likely mediated by the activation of the Nrf2/Keap1 (nuclear factor E2-related factor 2/Kelch-like ECH-associated protein 1) and GPx4 signalling pathways." (PMID 40076493, 2025). "This was supported by the up-regulated expression levels of Nrf2, Keap1, and GPx4 mRNA and proteins in both mice with colitis and LPS-induced MCEC cells supplemented with GSH-Se." (PMID 40076493, 2025). "In DSS-induced colitis models, baicalein treatment upregulates key anti-ferroptotic defense molecules, including glutathione peroxidase 4 (GPX4), the cystine/glutamate antiporter subunit SLC7A11, and the transcription factor Nrf2." (PMID 41451362, 2025). "Collectively, it is suggested that enhancing the expression of HIF-1α can upregulate the level of GPX4 to inhibit ferroptosis in colonic epithelial cells, thereby improving colitis in mice." (PMID 40691131, 2025). "In detail, HT downregulated ACSL4 and PTGS2 mRNA and protein, while it upregulated Gpx4 mRNA and protein, suggesting that HT suppressed ferroptosis in colitis in vitro." (PMID 39064786, 2024). "Mice lacking LCN2 in ILC3s or administration of a p38 pathway inhibitor exhibited similar phenotypes of ILC3 and colitis to those observed in GPX4 conditional knock-out mice." (PMID 39300068, 2024). "Herein, we found that the number of AOM/DSS-induced colitis-associated CRC in PRDX1 knockout mice was significantly lower than that in wild-type mice, concomitant with the downregulation of NRF2 and GPX4." (PMID 39430237, 2024). "The experimental results with Fer-1 treatment demonstrated that the restoration of GPX4 expression and disruption of ferroptosis effectively ameliorated colitis symptoms in Lcn2fl/flRorccre mice." (PMID 39300068, 2024). "Our signaling study demonstrated that supplementation of Lactobacillus and Bifidobacterium blocked GPX4-mediated ferroptosis signaling, suggesting an important role of these gut microbiota in ferroptosis-mediated colitis." (PMID 39688910, 2024). "GPX4, a critical suppressor of ferroptosis, is a crucial target for investigating the involvement of ferroptosis in colitis pathogenesis." (PMID 39300068, 2024).
colitis (continued). "This suggests that PRDX1 deficiency suppressed AOM/DSS-induced colitis-associated CRC, possibly by enhancing ferroptosis, as the NRF2/GPX4 signalling pathway played a predominant role in orchestrating ferroptosis." (PMID 39430237, 2024). "Treatment with deferasirox for DSS‐induced colitis reduces oxidative stress, upregulates ferroptosis markers GPX4 and ferritin heavy chain (FTH), and promotes the production of SCFAs such as butyrate, valerate, isobutyrate, and isovalerate." (PMID 39568773, 2024). "Specifically, our findings indicate that LCN2 mediated the regulatory effect of ILC3s on colitis through the ATF4-xCT/GPX4 axis." (PMID 39300068, 2024). "Restoring GPX4 expression can alleviate ferroptosis and mitigate pathological changes in mouse colitis." (PMID 39300068, 2024). "Taken together, these data verified that PD ameliorates DSS-induced colitis by inhibiting ferroptosis activation via an Nrf2/Slc7a11/Gpx4-dependent signaling pathway." (PMID 39877390, 2024). "Our findings suggest that LCN2 specifically regulated ILC3s, particularly the NKp46+ILC3 subgroup, to secrete IL-22 and IL-17A by targeting GPX4, thereby exerting a protective effect on colitis." (PMID 39300068, 2024). "This study underscores the promise of employing nanotechnology-driven delivery systems to target GPX4 and regulate the glutathione-GPX4 pathway for the management of colitis." (PMID 39036600, 2024). "Early gut microbiota depletion exacerbates DSS‐induced colitis, marked by a reduction in anaerobes like Rikenella and Alistipes, along with decreased GPX4 and increased cyclooxygenase‐2 (COX‐2) and MDA levels." (PMID 39568773, 2024). "Other studies have shown that phlorizin and hesperetin alleviate DSS‐induced colitis by reducing iron overload and lipid peroxidation through the regulation of GPX4 and COX‐2." (PMID 39568773, 2024). "Our study revealed a positive correlation between NEDD4L protein expression and SLC3A2 in humans with IBDs and CRC, demonstrating that the NEDD4L/SLC3A2/GPX4 axis played an important role in colitis and CAC." (PMID 39688910, 2024). "Of note, in colitis aggravated by early-life microbial dysbiosis, we found that the protein levels of colonic GPX4 and COX-2, well-accepted markers of ferroptosis, show significant differences after DSS treatment." (PMID 37040489, 2023). "ω-6 PUFA in Western diet triggers GPX4-restricted mucosal inflammation resembling colitis via cytokine response and impaired GPX4 activity." (PMID 37868958, 2023). "We uncovered the inhibition of the SLC7A11/GSH/GPX4 antioxidant system in the colitis rats, of which the activity was enhanced by XJS treatment." (PMID 37153794, 2023). "SYD exerted significant alleviation effects of colitis, repression of inflammation and restoration of epithelial barrier function based on GPX4-regulated ferroptosis." (PMID 35974396, 2022). "BCP was demonstrated to alleviate colitis by increasing glutathione peroxidase 4 (GPX4) expression, GPX activity and GSH content, reducing the levels of malondialdehyde (MDA) and 4-hydroxynonenal (4-HNE) in the colon of UC mice." (PMID 36555694, 2022). "Knockout of GPX4 in rats further confirm that GPX4 is the target gene for SYD-induced anti-colitis effects." (PMID 35974396, 2022). "Different doses of SYD significantly alleviated colitis, decreased ferroptosis in epithelial cells, knockout of GPX4 significantly reversed SYD-induced alleviation effects on colitis, restoration of epithelial barrier function, and epithelial ferroptosis." (PMID 35974396, 2022). "Wogonoside, wogonin, palmatine, paeoniflorin and liquiritin were identified as active ingredients of SYD-exerted alleviation effects of colitis based on GPX4 agonistic transcription." (PMID 35974396, 2022). "Taken together, wogonoside, wogonin palmatine, paeoniflorin and liquiritin was identified as the key material basis of SYD-induced alleviation on colitis based on GPX4 agonistic activity." (PMID 35974396, 2022).